INSM1 (INSM transcriptional repressor 1)
Diseases named in the same sentence as INSM1 in open-access papers (continued):
Sharing a sentence is not in itself a finding about the gene and the disease.
NUT carcinoma (2 papers, 2023 to 2024). "Only a few studies have considered INSM1 expression in NUT carcinoma." (PMID 38326851, 2024). "INSM1 is a promising marker for SCLC and it was positive in all six NUT carcinoma cases available for staining as determined by immunohistochemistry." (PMID 38326851, 2024). "The positive ratio for INSM1 in NUT carcinoma was relatively high; however, the intensity was low without exception." (PMID 38326851, 2024).
pancreatic ductal adenocarcinoma (2 papers, 2021). An infiltrating adenocarcinoma that arises from the epithelial cells of the pancreas. "All TFs within the ADC TRN have been previously associated with the genesis of ADCs, in particular pancreatic ductal adenocarcinoma (PDA), with the exception of the insulinoma-associated protein 1 (INSM1)." (PMID 34094909, 2021).
paraganglioma (2 papers, 2021 to 2026). A benign or malignant neoplasm arising from paraganglia located along the sympathetic or parasympathetic nerves. "Histopathology confirmed paraganglioma with insulinoma-associated protein 1 (INSM1)-positive staining." (PMID 41994760, 2026). "However, large cytological series of paraganglioma cases did not study INSM1 expression as NE marker in cytological material." (PMID 34943408, 2021).
retinoblastoma (2 papers, 2015 to 2020). A malignant tumor that originates in the nuclear layer of the retina. "INSM1 expression was reported in childhood tumors including MB, retinoblastoma (RB), and NB." (PMID 26456864, 2015).
solitary fibrous tumor (2 papers, 2021). Solitary fibrous tumor (SFT) represents a diverse group of ubiquitous rare spindle cell neoplasms that may be benign or malignant and that most frequently arises from the pleura and peritoneum and rarely from other sites such as head and neck, liver and skeletal muscle. "Four (including 1 solitary fibrous tumor; SFT, 2 SEMNs and 1 neoplasm with FUS-CREM gene fusion) expressed INSM1." (PMID 34350470, 2021). "INSM1 was not shown to be useful for solitary fibrous tumor (SFT) diagnosis when compared to HTER and STAT6." (PMID 34943408, 2021).
adrenocortical carcinoma (1 paper, 2021). "Adrenocortical carcinoma cells were also found to express INSM1, but more data is likely necessary before conclusively determining that adrenocortical carcinoma consistently stains positive for INSM1." (PMID 34943408, 2021).
ameloblastoma (1 paper, 2025). The most common odontogenic tumor, arising from the epithelial component of the embryonic tooth and usually affecting the molar-ramus region of the mandible or maxilla. "Given the recent understanding of neuroendocrine characteristics, the immunoexpression of SYP and INSM1 in a limited number of tumor cells in this study signifies genuine neuroendocrine differentiation in ameloblastomas." (PMID 39937015, 2025). "Immunohistochemically, ameloblastomas often express CD56; however, novel neuroendocrine markers such as synaptophysin (SYP), insulinoma-associated protein 1 (INSM1), and chromogranin A (CgA) remain unexplored." (PMID 39937015, 2025). "Considering the known functions of CLU, our results suggest that it is closely linked to the differentiation of a subset of ameloblastoma cells into neuroendocrine-like cells that express SYP and INSM1." (PMID 39937015, 2025). "The ectopic expression of SYP and INSM1 in ameloblastomas seems to be a unique example of SYP and INSM1 expression." (PMID 39937015, 2025). "INSM1 was expressed in most instances and was positive in four out of five ameloblastomas." (PMID 39937015, 2025). "We analyzed 36 ameloblastoma specimens for CD56, SYP, CgA, and clusterin (CLU) and examined limited samples for INSM1 expression by performing immunohistochemistry, transmission electron microscopy, and reverse transcriptase-polymerase chain reaction." (PMID 39937015, 2025). "Additionally, the immunoexpression of INSM1, a second-generation neuroendocrine marker, in SYP-positive ameloblastomas further supports this finding, along with the ultrastructural presence of dense-core granules." (PMID 39937015, 2025). "INSM1-positive reactions could be found in SYP-positive specimens except for one case; however, the reactivity of ameloblastomas was weaker than that of pancreatic islet cells." (PMID 39937015, 2025). "Therefore, first of all, we investigated the nature of ameloblastomas using the classic and revised neuroendocrine markers, CD56, SYP, CgA, and INSM1, as well as the correlation between CLU and the expression of neuroendocrine markers." (PMID 39937015, 2025). "This study is the first to suggest neuroendocrine differentiation in a small subset of ameloblastomas, characterized by SYP positivity and CgA negativity, along with INSM1 immunoexpression, in line with the recent understanding of neuroendocrine characteristics in the WHO classification." (PMID 39937015, 2025). "This study is the first to suggest neuroendocrine differentiation in ameloblastomas, as indicated by SYP and INSM1 immunoexpression and the presence of dense-core granules, which are consistent with the recent World Health Organization classification of Head and Neck Tumors guidelines." (PMID 39937015, 2025).
angioimmunoblastic T-cell lymphoma (1 paper, 2022). A mature T-cell non-Hodgkin lymphoma, characterized by systemic disease and a polymorphous infiltrate involving lymph nodes and extranodal sites. "At transcription level, INSM1 expression in AITL (angioimmunoblastic T-cell lymphoma) was higher than their adjacent normal tissues as well as Hodgkin's lymphoma." (PMID 36531655, 2022).
angiosarcoma (1 paper, 2022). A malignant tumor arising from the endothelial cells of the blood vessels. "Although the proportion was only 26% in angiosarcomas, we cannot ignore the presence of angiosarcomas with abnormal INSM1 expression, especially when evaluating poorly differentiated and inadequately sampled samples." (PMID 36531655, 2022).
brain tumor (1 paper, 2025). "Remarkably, INSM1 RNAi significantly inhibited brain tumor formation by PRO eNSCs." (PMID 41354838, 2025).
ganglioglioma (1 paper, 2023). A well differentiated, slow growing neuroepithelial neoplasm composed of neoplastic, mature ganglion cells and neoplastic glial cells. "INSM1 was positive in one pilocytic astrocytoma (2% of cells, mHS = 2) and 4 gangliogliomas (range 1–3.15% of cells, range mHS 1–9.5)." (PMID 37568909, 2023).
gastric neuroendocrine neoplasm (1 paper, 2025). A neoplasm with neuroendocrine differentiation that arises from the stomach. "Gastric neuroendocrine neoplasms typically exhibit positive immunohistochemical staining for chromogranin A, synaptophysin, and INSM-1." (PMID 40248085, 2025).
genitourinary neoplasms (1 paper, 2021). "Overall, in genitourinary neoplasms, INSM1 was more sensitive to small cell NEC compared to large cell NECs." (PMID 34943408, 2021).
glial neoplasms (1 paper, 2023). "Consistently, only one INSM1-positive case was observed among glioses in TMA when compared to immunoreactivity in 65% of gliomas." (PMID 37568909, 2023). "We postulated that immunohistochemical detection of proteins expressed preferentially in gliomas (EGFR, MEOX2, CD34) or during embryonal development (SOX11, INSM1) can be used to distinguish reactive gliosis from glioma." (PMID 37568909, 2023). "Compared to glioses, glial neoplasms were significantly more often positive (p < 0.001, χ2) for EGFR (33.8%), MEOX2 (48.9%), SOX11 (69.9%) and INSM1 (64.9%)." (PMID 37568909, 2023). "After excluding IDH1 R132H mutant gliomas from the analysis, the specificity increased to 41.5% for EGFR, 53.2% for MEOX2, 50.7% for SOX11 and 57.3% for INSM1." (PMID 37568909, 2023). "Glial neoplasms were significantly more often (p < 0.001, χ2) positive for EGFR (34.1% vs. 0%), MEOX2 (49.3% vs. 2.3%), SOX11 (70.5% vs. 20.4%), and INSM1 (65.4% vs. 2.3%)." (PMID 37568909, 2023). "INSM1 is not detected in the adult brain tissue samples but it is present in some gliomas." (PMID 37568909, 2023).
Gliosis (1 paper, 2023). Gliosis is the focal proliferation of glial cells in the central nervous system. "The sensitivity and specificity of the negative staining for the diagnosis of gliosis were as follows: EGFR—100% sensitive, 32.8% specific; MEOX2—97.7% sensitive, 37.5% specific; SOX11—79.5% sensitive, 46.6% specific and INSM1—97.7% sensitive, 47.8% specific." (PMID 37568909, 2023).
Hodgkins lymphoma (1 paper, 2022). A heterogeneous group of malignant lymphoid neoplasms of B-cell origin characterized histologically by the presence of Hodgkin and Reed-Sternberg (HRS) cells in the vast majority of cases. "Our study confirmed that there were statistically significant differences in the positive rate of INSM1 between AITL/Hodgkin's lymphomas and DDLPS/WDLPS, which may assist in the differential diagnosis of these tumors." (PMID 36531655, 2022). "INSM1 expression in AITL was significantly higher than Hodgkin's lymphoma (P = 0.008)." (PMID 36531655, 2022). "There were significant differences in the expression of INSM1 between AITL and Hodgkin's lymphoma and WDLPS and DDLPS." (PMID 36531655, 2022). "We found that the mRNA and protein levels of INSM1 were significantly different between AITL and Hodgkin's lymphoma." (PMID 36531655, 2022). "INSM1 may contribute to diagnosis between AITL and Hodgkin's lymphoma, but more clinical practice is needed." (PMID 36531655, 2022). "In this study, we found that INSM1 might help in the differential diagnosis between AITL and Hodgkin's lymphoma." (PMID 36531655, 2022).
invasive carcinoma (1 paper, 2021). A carcinoma that is not confined to the epithelium, and has spread to the surrounding stroma. "At this age, prostates of PRN mice contained primarily HGPIN, as well as foci of AR-/INSM1- invasive carcinoma." (PMID 34099734, 2021).
lymphoma (1 paper, 2025). A malignant (clonal) proliferation of B- lymphocytes or T- lymphocytes which involves the lymph nodes, bone marrow and/or extranodal sites. "First, when classical neuroendocrine markers are absent, diagnosis should integrate morphology with a focused IHC panel centered on CD56 and a sustentacular S100 rim, supplemented by INSM1 for sensitivity and exclusion of lymphoma through EBER and cytotoxic markers." (PMID 41293333, 2025).
metastatic melanoma (1 paper, 2021). A melanoma that has spread from its primary site to another anatomic site. "Further tumor immunohistochemistry revealed extensive neuroendocrine differentiation with CD56, synaptophysin, and INSM1, as well as strong immunoreactivity for melanocyte markers including SOX10, S100, PRAME, and MITF, consistent with metastatic melanoma with neuroendocrine differentiation." (PMID 34926265, 2021).
mucinous carcinoma (1 paper, 2021). "INSM1 expression was found in all solid papillary carcinoma cases (5% to 99% nuclear expression), while mucinous carcinomas showed minimal nuclear expression (1% to 5%)." (PMID 34943408, 2021).
neuroendocrine neoplasms of the pancreas (1 paper, 2022). "Common to neuroendocrine neoplasms of the pancreas is their expression of synaptophysin, chromogranin A, and/or INSM1." (PMID 34647171, 2022).
neuroepithelial neoplasm (1 paper, 2025). A neoplasm of the nervous system that arises from the neuroepithelial tissues. "INSM1 was identified as a potent NE biomarker highly elevated in NE and neuroepithelial neoplasms." (PMID 41514864, 2025).
pituitary carcinoma (1 paper, 2020). A primary or metastatic malignant neoplasm affecting the pituitary gland. "By immunohistochemistry, all liver metastases from pituitary carcinoma were positive for T-PIT, OSCAR and the neuroendocrine markers chromogranin and INSM1." (PMID 32622369, 2020).
prostate adenocarcinoma (1 paper, 2021). "Moreover, it is highly specific considering that only 3.4% of benign prostate tissues and 4.0% of prostate adenocarcinomas stained positive for INSM1." (PMID 34943408, 2021). "Moreover, it was quite specific, since only 3.4% of benign prostate tissues and 4.0% of prostate adenocarcinomas stained positive for INSM1." (PMID 34943408, 2021).
prostate small cell carcinoma (1 paper, 2021). A neuroendocrine carcinoma of the prostate gland with unfavorable prognosis, composed of small cells containing neurosecretory granules. "For prostate small cell carcinoma, INSM1 has been shown to be more sensitive (92.3%, 12/13) compared to SYP (84.6%, 11/13) and CgA (53.8%, 7/13), making it the superior NE marker for prostate small cell carcinoma." (PMID 34943408, 2021). "INSM1 has also been shown to be more sensitive (92.3%) than both SYP (84.6%) and CGA (53.8%) in prostatic small cell carcinomas, making it a superior NE biomarker." (PMID 34943408, 2021).
rectal NETs (1 paper, 2021). "Moreover, insulinoma-associated protein 1 (INSM1) has recently been reported to be an marker specifically expressed by rectal NETs." (PMID 33923121, 2021).
soft tissue sarcoma (1 paper, 2022). A malignant neoplasm arising from muscle tissue, adipose tissue, blood vessels, fibrous tissue, or other supportive tissues excluding the bones. "However, recent studies show that INSM1 can also be expressed in a variety of non-NE neoplasms, including soft tissue sarcomas, where INSM1 is detected generally more commonly than other NE markers." (PMID 34663914, 2022).
sweat gland carcinoma (1 paper, 2025). A carcinoma arising from the sweat glands. "For instance, TRPS1 co-expression with neuroendocrine markers(e.g., INSM1, Syn) strongly supports endocrine mucin-producing sweat gland carcinoma (EMPSGC)." (PMID 40969274, 2025).
thymic carcinoma (1 paper, 2023). Thymic carcinoma (TC) is a type of thymic epithelial neoplasm characterized by a high malignant potential. "When we examined the expression of these genes in TETs, we found that INSM1 showed a significant expression in thymic carcinomas compared to thymomas, which aligns with the findings of a previous study." (PMID 38201543, 2023). "Furthermore, general neuroendocrine markers, including the new marker, INSM1, can be expressed in thymic carcinomas." (PMID 38201543, 2023).
thyroid (1 paper, 2021). "Novel neuroendocrine and C cell markers, such as INSM-1, ISL1, secretagonin, and FOXA1, are upcoming in thyroid oncopathology practice and under investigation." (PMID 35008368, 2021).
triple-negative breast carcinoma (1 paper, 2020). An invasive breast carcinoma which is negative for expression of estrogen receptor (ER), progesterone receptor (PR), and human epidermal growth factor receptor 2 (HER2). "The expression of INSM1 was significantly increased in luminal A and triple negative breast cancer tissues compared with paracancerous tissues." (PMID 32670859, 2020). "In our study, INSM1 was highly expressed in the luminal A and triple negative breast cancer tissues and cells." (PMID 32670859, 2020). "The levels of INSM1 mRNA were significantly increased in luminal A and triple negative breast cancer tissues." (PMID 32670859, 2020).
tumor (94 papers, 2014 to 2026). "The tumor demonstrated large cell morphology, high mitotic activity (Ki-67 index of 50%), and strong expression of neuroendocrine markers, including Insulinoma-Associated Protein 1 (INSM1)." (PMID 41357569, 2025). "We discovered that INSM1 keeps tumor cells in an immature, stem-like state and is closely linked to a chemical pathway called the methionine cycle, which affects gene regulation through epigenetic changes." (PMID 41514864, 2025). "Immunohistologically, the tumor cells were positive for the neuroendocrine markers synaptophysin and insulinoma-associated protein 1 (INSM1) and demonstrated an antigen Kiel 67 (Ki-67) proliferation rate of 100%." (PMID 41333490, 2025). "Tumor cells were strongly and diffusely positive for synaptophysin (Syn), chromogranin A (CgA), and insulinoma-associated protein 1 (INSM1)." (PMID 40761271, 2025). "In high-risk NB, elevated INSM1 expression reflects a developmental arrest, with tumor cells retaining an immature, progenitor-like phenotype." (PMID 41514864, 2025). "Patchy staining for neuroendocrine markers such as INSM1 and synaptophysin can present a diagnostic pitfall, particularly when a tumor exhibits a monotonous epithelioid morphology with vesicular chromatin." (PMID 39404971, 2024). "The tumor cells were positive for synaptophysin, chromogranin, insulinoma-associated protein 1 (INSM-1), and thyroid transcription factor 1 (TTF-1)." (PMID 39022484, 2024). "The tumor cells showed positivity for neuroendocrine markers such as synaptophysin, chromogranin A and insulinoma-associated protein 1 (INSM1) with a Ki-67 index of 60.6%, indicating the cells to be NEC." (PMID 37027114, 2023). "Diffuse and intense cytoplasmic expression of synaptophysin and chromogranin A and nuclear staining for insulinoma-associated 1 (INSM1) reveals the tumor’s neuroendocrine differentiation, the common denominator of NENs." (PMID 34647171, 2022). "Histopathological examination of the tumor following alectinib resistance revealed a poorly differentiated carcinoma with insulinoma associated protein 1 (INSM1) expression." (PMID 34660278, 2021). "Using mice that share a common driver oncogene, we show that tumor subtype is also influenced by naturally occurring genetic diversity, in the form of distinct alleles of the Insm1 gene." (PMID 30796198, 2019). "The strong association of INSM1 expression with childhood tumors including NB was reported, exemplifying the current embryonic tumor model." (PMID 26456864, 2015). "Immunohistochemically, the tumor showed strong and diffuse expression of all commonly used neuroendocrine markers, including chromogranin A, synaptophysin, syntaxin-1, and insulinoma-associated protein 1 (INSM1)." (PMID 40648806, 2025). "The interplay between INSM1 and N-Myc in high-risk NB promotes malignant aggression of tumor cells." (PMID 37627018, 2023). "In addition, 50 tumors were immunostained for the novel diagnostic marker INSM1, which yielded a predominantly strong and diffuse nuclear reactivity in all analyzed cases: staining was observed in at least 80% of tumor cells in all cases." (PMID 35551625, 2022). "Therefore, targeting the INSM1/N-Myc-associated signaling axis should be a feasible approach to identifying new drugs for the suppression of NB tumor growth." (PMID 36290282, 2022). "Diagnosis was confirmed through histopathology and immunohistochemistry (IHC), including synaptophysin, INSM1, and a Ki-67 index near 100%, consistent with a highly proliferative tumor and aggressive biologic behavior." (PMID 42255800, 2026). "We have shown that N-Myc transcriptionally activates INSM1, and in turn, INSM1 stabilizes N-Myc protein, forming a feed-forward loop that promotes tumor growth and aggressive malignancy." (PMID 41514864, 2025). "To investigate changes in the INSM1 gene expression network during tumor evolution, we first determined the trajectory of tumor subpopulations." (PMID 41354838, 2025).